EGFR (epidermal growth factor receptor)
Diseases named in the same sentence as EGFR in open-access papers (continued):
Sharing a sentence is not in itself a finding about the gene and the disease.
bladder cancer (continued). "Also, the combination of weekly dosing of an EGFR inhibitor together with an NSAID has looked striking in preclinical models of colon and bladder cancer." (PMID 37169023, 2023). "As a pure aside, most of our early studies in bladder used erlotinib and gefitinib because our model paralleled human basal bladder cancer and overexpressed EGFR but not HER2." (PMID 37169023, 2023). "To study the contribution of HOTAIR and its potential upstream EGFR-ProT axis to cisplatin-induced bladder cancer cachexia, we first asked whether HOTAIR, ProT, and EGFR were overexpressed in clinical bladder tumor tissues." (PMID 36471329, 2022). "conjugated the EGFR-specific and FDA-approved mAb Panitumumab via NHS ester chemistry with IRDye 700Dx, generating Panitumumab-IR700, intending to create a targeted phototherapy, termed photoimmunotherapy (PIT) for bladder cancer." (PMID 34123841, 2021). "In AR-positive bladder cancer cells, DHT could activate the epidermal growth factor receptor (EGFR)/ERBB2/ERK pathway in the presence of the epidermal growth factor (EGF)." (PMID 33919565, 2021). "Three main signaling pathways are found to be the downstream of EGFR: the Ras/Raf/MAPK pathway, the PI3K/AKT/mTOR pathway, and the STAT pathway, aberrant activation of these pathways responds to tumorigenesis in several solid tumors including bladder cancer." (PMID 35004854, 2021). "This agrees with Eriksson and colleagues who concluded that the application of EGFR/HER2 inhibitors did not adequately consider the molecular heterogeneity of bladder cancers in clinical trials." (PMID 32978523, 2020). "Studies have shown the potential prognostic value of markers including receptor tyrosine kinases such as fibroblast growth factor receptor 3 (FGFR3), epidermal growth factor receptor (EGFR), and ERBB2/human epidermal growth factor receptor 2 (HER2) in invasive bladder cancers." (PMID 33312739, 2020). "For example, in bladder cancer, ERK-mediated activation by the EGFR decreases miR-23b." (PMID 33081077, 2020). "Therefore, four overlapping genes (EGF, EGFR, VEGFA, and THBS1) were extracted from the bladder cancer and PI3K–AKT pathways." (PMID 30868054, 2019). "Frequency of over expression in bladder cancer has not been studied in our population; therefore we aimed to evaluate the frequency and prognostic significance of EGFR immunohistochemical expression in locoregional population." (PMID 29879970, 2018). "The cytotoxicity of 111In delivered by the EGFR-targeted MNT (111In-MNT) was greatly enhanced on EJ-, HT-1376-, and 5637-expressing EGFR bladder cancer cell lines compared with 111In non-targeted control." (PMID 30510514, 2018). "In this study, we aim to develop and manufacture a type of anti-EGFR ICG-MMC-encapsulated perfluorocarbon (PFC) double nanoemulsion (EIMPDNE) to explore the impact of joint photo and chemotherapeutics on EGFR-expressing bladder cancer cells." (PMID 29701711, 2018). "In terms of UCC, EGFR is overexpressed in up to 74% of bladder cancer cells, but has a relatively low expression level in normal urothelium." (PMID 29701711, 2018). "Medical trials have, however, not shown effectiveness when testing EGFr blockade in the therapy of urinary bladder cancer." (PMID 29508172, 2018). "In contrast to lung cancer, EGFR inhibitors have not shown a significant efficacy in bladder cancer patients; therefore, it is urgent to develop a novel therapeutic strategy to improve the effectiveness of EGFR inhibitors in bladder cancer treatment." (PMID 28165387, 2017). "In the current study, we found that XIAP BIR domain could regulate EGFR expression through downregulating miR-200a by targeting protein phosphatase 2 (PP2A)/c-Jun axis and further promoted the bladder cancer cell anchorage-independent growth." (PMID 28057023, 2017). "To investigate the functional interplay between XIAP and EGFR, we first examined whether XIAP affected EGFR expression levels in human bladder cancer cells." (PMID 28057023, 2017).
bladder cancer (continued). "As luminal and basal bladder cancer subtypes are suspected to present a subtype specific overexpression of other well known drug targets like the FGFR, EGFR and ERBB gene families, the number of promising personalized therapy options rises for FOXM1 enriched MIBC." (PMID 28498805, 2017). "EGFR is a potential therapeutic target for treating bladder cancer, but has not been approved for clinical use yet." (PMID 27334428, 2016). "Preclinical studies demonstrated that TGFα-immunotoxins are highly cytotoxic to bladder cancer cells and patient bladder cancer explants, despite the lack of EGFR amplification in these cells." (PMID 27153091, 2016). "We demonstrated that androgen upregulated the expression of EGFR and ERBB2 as well as the levels of phosphorylation of their downstream proteins AKT and extracellular signal-regulated kinase- (ERK-) 1/2 via the AR pathway in bladder cancer cells." (PMID 26770009, 2015). "EGFR, a potential prognostic marker for MIBC has also been widely studied in bladder cancer." (PMID 26250800, 2015). "Accordingly, the levels of EGFR and downstream major mediators were investigated to determine whether alterations in EGFR-AKT are involved in the role of miR-424 in bladder cancer." (PMID 26090723, 2015). "There is limited effect of tyrosine kinase inhibitors or “naked” antibodies binding EGFR or HER2 for therapy of metastasized urinary bladder cancer and these methods are therefore not routinely used." (PMID 25810701, 2015). "In a bladder cancer cell line the stable expression of miR-200s increased E-cadherin levels, decreased expression of ZEB-1, ZEB-2, and cell migration, and increased sensitivity to EGFR-blocking agents." (PMID 25058589, 2014). "Although mechanism by which EGFR regulates tumor biology in bladder cancer is not clearly defined, it has been demonstrated that EGFR signalling regulates cell survival, proliferation, differentiation, and invasion." (PMID 23409107, 2013). "In bladder cancer cells, we here showed that EGF could activate AR transcription and PD168393, a specific inhibitor of EGFR, restored this EGF effect." (PMID 22922989, 2012). "We have recently shown that AR activation results in upregulation of EGFR and ERBB2 expression in bladder cancer cells, which may play an important role in androgen-mediated tumor progression." (PMID 22922989, 2012). "For instance, MAPK phosphorylation was not inhibited in an EGFR-positive, gefitinib-resistant human bladder cancer cell line upon gefitinib treatment, while MAPK phosphorylation decreased in an EGFR-positive, gefitinib-sensitive cell line." (PMID 20037743, 2010). "Disparate clinical results for EGFR and HER2 targeted therapies in MIBC is most likely explained by the underlying heterogeneity of bladder cancer and the lack of adequate molecular descriptions of its molecular subtypes; the context in which the HER2 and EGFR targets operate." (PMID 36737799, 2023). "These hub nodes such as VEGFA and EGFR were mainly enriched in GO functions including positive regulation of MAP kinase activity, activation of protein kinase activity, regulation of MAP kinase activity, and pathways like proteoglycans in cancer, bladder cancer, and estrogen signaling." (PMID 32256653, 2020). "Hence, squamous-differentiated bladder cancer appears to be oncogenically addicted to EGFR activity and consequently sensitive to both EGFR inhibition and knockdown without any short-term escape mechanisms, thereby suggesting a putative “Achilles heel”." (PMID 32978523, 2020).
bladder cancer (continued). "Since EGFR and HER2 are predominantly expressed in the basal and luminal subtypes of bladder cancer, respectively, combining both targets provide a novel and highly selective way of targeting bladder cancers that may have moderate expression of both." (PMID 30765854, 2019). "When we treated T24 human bladder cancer cells with 5 μM of these EGFR inhibitors, the CCK-8 assay showed that neither lapatinib nor gefitinib could reduce cell viability in a time-dependent manner." (PMID 28165387, 2017). "Since miR-200a binds to the 3′-UTR of EGFR mRNA and inhibits EGFR protein translation, the attenuation of miR-200a expression by BIR domain of XIAP results in the enhancement of EGFR protein translation and increases the anchorage-independent growth of the bladder cancer cells." (PMID 28057023, 2017). "Despite the potential therapeutic efficacy of epithelial growth factor receptor (EGFR) inhibitors in the treatment of advanced stage bladder cancer, there currently is no clear evidence to support this hypothesis." (PMID 28165387, 2017). "Bladder cancers overexpress EGFR, while normal bladder epithelium expresses little or no EGFR suggesting that these cancers may too be susceptible to an EGFR-directed therapy." (PMID 27153091, 2016). "Thirdly, depletion of p27Kip1 in p27Kip1-expressing MEFs results in a dramatic up-regulation of EGFR expression, suggesting that p27Kip1-regulated EGFR expression is not only operative in bladder cancer cells, but also in non-bladder cancer and non-cancer cells." (PMID 25121353, 2014). "Taken together, our findings provide us with an insight into LRIG1 function, and we conclude that LRIG1 evolved in bladder cancer as a rare feedback negative attenuator of EGFR, thus could offer a novel therapeutic target to treat patients with bladder cancer." (PMID 24314030, 2013). "Moreover, the results suggest that overexpression of EGFR is usually a late event in bladder cancer development related to genetic instability rather than an early event in malignant transformation." (PMID 7911031, 1994). "PGRN was found to replace the typical ligand of EphA2-A1 in bladder cancer, phosphorylation of EphA2 Ser897 induced by PGRN binding to EphA2 might induce crosstalk between other receptor tyrosine kinases, including other Eph receptors and epidermal growth factor receptor (EGFR)." (PMID 37660003, 2023). "Moreover, EGFR is overexpressed in up to 74% of bladder cancer tissue specimens but has a relatively low expression in normal urothelium suggesting that it could be a potential therapeutic target." (PMID 34911571, 2021). "The MLPA assay did contain sequences to analyze a limited number of genes, but of several exons; some genes that may have an important role in bladder cancer progression were not included in this assay, e.g. the androgen receptor, which may contribute to disease progression by EGFR signaling." (PMID 33298978, 2020). "Similarly, antibody conjugates such as the EGFR humanized chimeric monoclonal antibody C225 (cetuximab) conjugated to a benzoprophyrin derivative (verteprofrin) are also non-specific, making selective treatment of bladder cancer challenging." (PMID 30765854, 2019). "We analyzed and discussed in this article whether EGFR and HER2 are expressed with such high frequencies that targeted radionuclide therapy might be a possibility and an alternative or complement to other modalities in the treatment of metastatic urinary bladder cancers." (PMID 25810701, 2015). "Moreover, PDGFRB rather than FGFR2 could form a heterodimer with EGFR on bladder cancer cells, and this could induce resistance to anti-EGFR therapy for bladder cancer." (PMID 24801713, 2014). "By analyzing TCGA data from 408 bladder cancer patients, we found a positive correlation between ProT and HOTAIR (r = 0.108, p = 0.029) but not between EGFR and HOTAIR (r = − 0.039, p = 0.434) nor between EGFR and ProT (r = − 0.065, p = 0.191)." (PMID 36471329, 2022).
bladder cancer (continued). "A factor contributing to the disparate results is most likely the underlying heterogeneity of bladder cancer and the lack of adequate molecular descriptions of bladder cancer molecular subtypes; the context in which the ERBB2 and EGFR targets operate." (PMID 28388586, 2017). "Elevated phosphorylation of AKT1/2 is observed in 40–50% of bladder cancer cases, independent of PIK3CA or PTEN alterations, and may result from upstream receptor tyrosine kinase (e.g., FGFR3 or EGFR) activation." (PMID 41438986, 2025). "In consistence, a study investigating the expression of all HER-family members in bladder cancer found that while EGFR and HER2 expression rates alone do not correlate with survival, higher EGFR or HER2 expression combined with low HER3 and HER4 expression result in a worse prognosis." (PMID 34123841, 2021).
metastatic disease (327 papers, 1990 to 2026). "PD-L1 expression increased with advancing tumor stage and was positively associated with metastatic status, whereas EGFR levels declined in metastatic disease." (PMID 42203995, 2026). "Alterations in the EGFR are associated with poor prognosis and with an increased rate of tumor growth after treatment with anti-PD-1 agents in metastatic disease." (PMID 39148899, 2024). "The SMAD4 gene is frequently mutated in PCa, correlates with changes in altered histopathological transitions, metastatic disease, and poor prognosis and is associated with a higher mortality rate in patients receiving anti-EGFR/Akt/mTOR therapy." (PMID 38329726, 2024). "Upon comparing the single gene analysis results and tumour progressive score between the primary and the resected metastatic tumour, we observed EGFR exon 19 deletion in the both tumour but BRAF V600E mutations only in metastatic tumour." (PMID 39139611, 2024). "Osimertinib is a mutant-selective EGFR tyrosine kinase inhibitor, and NSCLC patients with a positive EGFR T790M mutation who have locally progressed or metastatic disease respond well to therapy." (PMID 39695171, 2024). "In 2021, mobocertinib was FDA-approved as the first drug for NSCLC patients with locally advanced or metastatic disease that had an EGFR exon 20 insertion mutations and progressed with platinum-based chemotherapy." (PMID 36902723, 2023). "Lazertinib received local approval in South Korea in 2021 for NSCLC patients with EGFR T790M mutations that had previously received treatment with EGFR inhibitors and that had locally advanced or metastatic disease." (PMID 36902723, 2023). "The evolutionary cancer cells acquire metastatic abilities, resulting in different EGFR mutation statuses in primary and metastatic tumors." (PMID 36457515, 2022). "Of the patients who had EGFR mutation-positive primary tumors, two (11.1%) had different mutations in the metastatic tumors." (PMID 35912248, 2022). "Yet, the incidence of EGFR mutations doubles in metastatic disease (to around 30.3%), while the frequency of KRAS mutations remains constant (around 29%)." (PMID 35806218, 2022). "The de novo resistance groups were significantly associated with metastatic disease at presentation (96.4%; p-value 0.003) and uncommon EGFR mutation subtype (25%; p-value 0.001)." (PMID 35140316, 2022). "The presence of synchronous metastases at first diagnosis was associated with a significantly poorer OS in the anti-EGFR subgroup compared to patients with metachronous metastatic disease (HR 3.01, 95% CI 1.29–7.04, p < 0.05)." (PMID 35406413, 2022). "Third, the different microenvironments of primary and metastatic tumors can independently influence the evaluation process of tumor cells, leading to the gain or loss of EGFR mutations." (PMID 36457515, 2022). "No previous studies have reported an association between the EGFR mutation status of metastatic tumors and responsiveness to EGFR-TKIs in NSCLC." (PMID 36457515, 2022). "Prior studies have shown a benefit to continuing to treat patients on TKI therapy despite limited progression of one or more sites of metastatic disease in EGFR-mutated NSCLC." (PMID 36010982, 2022). "There are clinical data supporting the continuation of patients on TKI therapy despite limited progression of one or more sites of metastatic disease in EGFR-mutated NSCLC." (PMID 36010982, 2022). "Long anti-EGFR free interval, previous response to anti-EGFR therapy, and previous lines >2 for metastatic disease were associated with clinical outcome in the univariate analysis." (PMID 35530345, 2022). "In the 12 EGFR-mutated patients with metastatic disease, the most frequent metastatic site was bone (5 patients) followed by brain (4 patients), lungs (4 patients), pleura (3 patients), liver (2 patients), and adrenal gland (1 patient)." (PMID 34696229, 2021).